RFFL (ring finger and FYVE like domain containing E3 ubiquitin protein ligase)
Description:
E3 ubiquitin-protein ligase that regulates several biological processes through the ubiquitin-mediated proteasomal degradation of various target proteins. Mediates 'Lys-48'-linked polyubiquitination of PRR5L and its subsequent proteasomal degradation thereby indirectly regulating cell migration through the mTORC2 complex. Ubiquitinates the caspases CASP8 and CASP10, promoting their proteasomal degradation, to negatively regulate cell death downstream of death domain receptors in the extrinsic pathway of apoptosis. Negatively regulates the tumor necrosis factor-mediated signaling pathway through targeting of RIPK1 to ubiquitin-mediated proteasomal degradation. May also play a role in endocytic recycling.
Synonyms: CARP-2; Fring; RNF189; RNF34L; rififylin; CARP2
Tractability: Antibody: its Gene Ontology location is reachable by antibodies, with high confidence; UniProt places it where antibodies can reach, with medium confidence. PROTAC: UniProt records ubiquitination sites on it; ubiquitination databases record sites on it.
Gene: Protein-coding gene on chromosome 17 (35,005,990 to 35,089,899, reverse strand). Ensembl gene ENSG00000092871.
Subcellular location: Cytoplasm, cytosol; Cell membrane; Recycling endosome membrane
Subcellular location (Human Protein Atlas): Vesicles
Gene Ontology:
Molecular function: protease binding; protein binding; protein kinase binding; ubiquitin protein ligase activity; ubiquitin protein ligase binding
Biological process: negative regulation of extrinsic apoptotic signaling pathway via death domain receptors; negative regulation of tumor necrosis factor-mediated signaling pathway; proteasome-mediated ubiquitin-dependent protein catabolic process; protein K48-linked ubiquitination; ubiquitin-dependent protein catabolic process; regulation of fibroblast migration; regulation of TOR signaling; protein ubiquitination
Cellular component: cytoplasm; endosome membrane; Golgi membrane; lysosome; membrane; plasma membrane; nucleoplasm; cytoplasmic vesicle; cytosol; recycling endosome membrane
Genetic constraint (gnomAD): Loss-of-function variants: 15 observed, 37.57 expected, observed/expected ratio (o/e) 0.4, 90% interval 0.27 to 0.62. The upper end of that interval is the gene's LOEUF score, 0.62, which puts it in group 2 of 6, group 1 being the genes least tolerant of losing a copy. Missense variants: 348 observed, 445.11 expected, observed/expected ratio (o/e) 0.78, 90% interval 0.71 to 0.85. Synonymous variants: 146 observed, 165.84 expected, observed/expected ratio (o/e) 0.88, 90% interval 0.77 to 1.01.
Homologues: Orthologues: chimpanzee RFFL (99% identical), macaque RFFL (98% identical), guinea pig RFFL (91% identical), rabbit RFFL (91% identical), pig RFFL (91% identical), rat Rffl (90% identical), mouse Rffl (90% identical), zebrafish rffl (55% identical), tropical clawed frog rffl (51% identical), zebrafish RFFL (41% identical), Drosophila melanogaster CG17019 (38% identical). Paralogues in human: RNF34 (44% identical).
Diseases named in the same sentence as RFFL in open-access papers:
RFFL is named in the same sentence as 8 diseases in open-access papers, as found by Europe PMC text mining. Sharing a sentence is not in itself a finding about the gene and the disease. The quoted sentences say what the papers report.
colorectal cancer (1 paper, 2018). A primary or metastatic malignant neoplasm that affects the colon or rectum.
cystic fibrosis (1 paper, 2023). Autosomal recessive disorder caused by pathogenic variants in the CFTR gene (cystic fibrosis transmembrane conductance regulator), which encodes a chloride and bicarbonate channel expressed in epithelial cells, and follow the diagnosis criteria. "Interestingly, HS6ST1 and RFFL have been associated with lung diseases, namely idiopathic pulmonary fibrosis and cystic fibrosis, respectively." (PMID 37686257, 2023).
tumor (3 papers, 2013 to 2023). "The increased expression of anti-apoptotic genes, including EIF3H, RFFL and HDAC2, may favorably assist uncontrolled cell growth and proliferation to enhance tumor growth in patients with HCC-R." (PMID 24377043, 2013).
RFFL also shares sentences with these, for which no sentence is quoted: cancer (2 papers); breast carcinoma (1); Duchenne muscular dystrophy (1); idiopathic pulmonary fibrosis (1); lung diseases (1).